H2AZ1 (H2A.Z variant histone 1)
Description:
Variant histone H2A which replaces conventional H2A in a subset of nucleosomes. Nucleosomes wrap and compact DNA into chromatin, limiting DNA accessibility to the cellular machineries which require DNA as a template. Histones thereby play a central role in transcription regulation, DNA repair, DNA replication and chromosomal stability. DNA accessibility is regulated via a complex set of post-translational modifications of histones, also called histone code, and nucleosome remodeling. May be involved in the formation of constitutive heterochromatin. May be required for chromosome segregation during cell division.
Synonyms: H2A/z; H2AFZ; H2AZ; H2A.Z; H2A.Z-1
Tractability: Small molecule: a structure with a bound ligand is known. PROTAC: UniProt records ubiquitination sites on it; ubiquitination databases record sites on it.
Gene: Protein-coding gene on chromosome 4 (99,948,069 to 99,950,367, reverse strand). Ensembl gene ENSG00000164032.
Subcellular location: Nucleus; Chromosome
Subcellular location (Human Protein Atlas): Nucleoplasm
Pathways (Reactome):
Immune System: FXIIa activates plasma kallikrein-kinin system
Metabolism of proteins: Amyloid fiber formation
Gene Ontology:
Molecular function: chromatin DNA binding; nucleosomal DNA binding; protein binding; RNA polymerase II cis-regulatory region sequence-specific DNA binding; RNA polymerase II core promoter sequence-specific DNA binding; structural constituent of chromatin; DNA binding; protein heterodimerization activity
Biological process: cellular response to estradiol stimulus; positive regulation of transcription by RNA polymerase II; chromatin organization; heterochromatin formation
Cellular component: Barr body; euchromatin; extracellular exosome; heterochromatin; nucleoplasm; nucleosome; nucleus; chromosome
Genetic constraint (gnomAD): Loss-of-function variants: 0 observed, 7.49 expected, observed/expected ratio (o/e) 0, 90% interval 0 to 0.4. That is too few expected variants to judge how well the gene tolerates losing a copy. Missense variants: 18 observed, 105.92 expected, observed/expected ratio (o/e) 0.17, 90% interval 0.12 to 0.25. Synonymous variants: 49 observed, 43.17 expected, observed/expected ratio (o/e) 1.13, 90% interval 0.9 to 1.44.
Homologues: Orthologues: chimpanzee H2AZ1 (100% identical), macaque H2AZ1 (100% identical), guinea pig H2AZ1 (98% identical), Drosophila melanogaster His2Av (95% identical). Paralogues in human: H2AZ2 (98% identical), H2AC18 (62% identical), H2AC19 (62% identical), H2AC25 (62% identical), H2AC6 (62% identical), H2AC1 (62% identical), H2AC11 (62% identical), H2AC12 (62% identical), H2AC13 (62% identical), H2AC14 (62% identical), H2AC15 (62% identical), H2AC16 (62% identical), and 15 more.
Diseases named in the same sentence as H2AZ1 in open-access papers:
H2AZ1 is named in the same sentence as 25 diseases in open-access papers, as found by Europe PMC text mining. Sharing a sentence is not in itself a finding about the gene and the disease. The quoted sentences say what the papers report.
hepatocellular carcinoma (5 papers, 2016 to 2024). A malignant tumor that arises from hepatocytes. "This suggests that the overexpression of H2AZ1 in hepatocellular carcinoma may indirectly regulate oxidative stress by targeting TFs such as SIRT1 and YY1." (PMID 38305811, 2024).
glioma (1 paper, 2022). A benign or malignant brain and spinal cord tumor that arises from glial cells (astrocytes, oligodendrocytes, ependymal cells). "Since the H2AZ1 and H2AZ2 isoforms share many similarities in their genome-wide occupancy and protein interactions, we speculate that both isoforms would regulate glioma proliferation." (PMID 35058574, 2022).
cancer (27 papers, 2013 to 2026). A tumor composed of atypical neoplastic, often pleomorphic cells that invade other tissues. "H2AZ1 is the most highly expressed histone variant within the H2A family and is overexpressed in various cancers, including prostate, bladder, non-small cell lung, breast, and colorectal cancers." (PMID 38305811, 2024). "Using alternative cellular models, we observed a significant decrease in cancer cell colony-forming ability after H2AZ1 knockout, and overexpression of H2AZ1(WT) partially restored the colony-forming ability, whereas overexpression of H2AZ1(MUT) did not." (PMID 38305811, 2024). "We observed a significant decrease in the colony-forming ability of cancer cells after H2AZ1 knockout." (PMID 38305811, 2024). "Notably, two distinct isoforms of H2AZ variant histone, namely H2AZ1 and H2AZ2 that are encoded by two non-allelic genes and differ only by three amino acids, are overexpressed in multiple cancers." (PMID 35058574, 2022).
tumor (8 papers, 2016 to 2024). "H2AZ1 overexpression in tumors is associated with a poor prognosis, suggesting its important role in tumor development and progression." (PMID 38305811, 2024). "Therefore, future research should focus on identifying and investigating the specific targets of H2AZ1 for tumor cell inhibition by knockdown or overexpression." (PMID 38305811, 2024). "Moreover, H2AZ1 knockdown resulted in a decrease in superoxide dismutase (SOD) activity and an increase in malondialdehyde (MDA) levels, suggesting that changes in H2AZ1 expression could affect oxidative stress in tumor cells." (PMID 38305811, 2024). "Furthermore, we observed that H2AZ1 knockdown significantly influenced tumor cell proliferation, cell cycle transition, and apoptosis, which may provide a foundation for understanding the biological functions of H2AZ1 in HCC." (PMID 38305811, 2024). "We found that H2AZ1 knockdown led to reduced superoxide dismutase (SOD) activity, elevated malondialdehyde (MDA) levels, and increased apoptosis rate in tumor cells (P < 0.001)." (PMID 38305811, 2024). "H2AZ1 overexpression in HCC may, thus, affect the development of tumor cells by regulating cell apoptosis, cell cycle, and aging." (PMID 38305811, 2024).
H2AZ1 also shares sentences with these, for which no sentence is quoted: breast carcinoma (7 papers); prostate carcinoma (6); melanoma (5); infection (4); colon cancer (3); liver cancer (3); autism (2); bladder cancer (2); brain tumor (1); Burkitt lymphoma (1); cardiac hypertrophy (1); cervical cancer (1); gastric cancer (1); intrahepatic cholangiocarcinoma (1); latent infection (1); lung carcinoma (1); malaria (1); migraine (1); prostatic adenocarcinoma (1); sarcoma (1); schizophrenia (1).